FBLN1 (fibulin 1)
Diseases named in the same sentence as FBLN1 in open-access papers (continued):
Sharing a sentence is not in itself a finding about the gene and the disease.
diabetes (14 papers, 2012 to 2025). "Previous studies have shown that elevated serum levels of fibulin-1 are associated with diabetes and impaired kidney function, as well as with hemodynamic cardiovascular risk markers." (PMID 40564116, 2025). "The calcium-binding glycoprotein fibulin-1 has been previously shown to increase with age and to be associated with diabetes, impaired kidney function, and hemodynamic cardiovascular risk markers." (PMID 37341993, 2023). "In conclusion, fibulin-1 is closely related to arterial stiffness caused by diabetes mellitus, and atherosclerosis." (PMID 35872882, 2022). "Fibulin-1 is associated with atherogenesis in diabetic patients, and at high levels fibulin-1 becomes an accurate indicator of cardiovascular risk in patients prior to acute cardiovascular events, obesity, or diabetes risk markers." (PMID 31214600, 2019). "In subgroup analysis, plasma fibulin-1 was associated with PWV in the diabetes group, (0.16 ± 0.07 m/s increase in PWV per 10 μg/mL increase in plasma fibulin-1, p<0.05), but not controls, β = 0.021 ± 0.057 m/s per 10 μg/mL, p = 0.70." (PMID 23866070, 2013). "The plasma concentration of fibulin-1 is a predictor of all cause and cardiovascular mortality in patients with diabetes mellitus." (PMID 23294625, 2013). "While it was shown that plasma fibulin-1 was able to predict all-cause mortality in patients with diabetes the underlying mechanisms which regulate the protein amount in certain disease entities are still uncertain." (PMID 23294625, 2013). "In summary, we demonstrate an increase in plasma fibulin-1 concentration in association with diabetes and impaired kidney function." (PMID 23294625, 2013). "In a multivariable Cox model including the predefined variables of age, LA volume, and diabetes, only fibulin-1 and a history of diabetes mellitus were associated with cardiac mortality." (PMID 23316326, 2012). "Fibulin-1, a circulating extracellular matrix glycoprotein, has been associated with arterial disease and elevated N-terminal prohormone B-type natriuretic peptide (NT-proBNP) in diabetes." (PMID 25014213, 2014). "We tested the hypothesis that plasma fibulin-1 levels are associated with cardiovascular risk markers in patients with chronic kidney disease and diabetes mellitus." (PMID 23294625, 2013). "First recently, fibulin-1 has been associated with arterial alterations in diabetes patients." (PMID 23866070, 2013). "Increased plasma fibulin-1 levels were associated with diabetes and impaired kidney function." (PMID 23294625, 2013). "Plasma fibulin-1 levels have been associated with N-terminal pro–B-type natriuretic peptide levels and left atrial size and shown to be predictive of mortality in patients with diabetes." (PMID 23316326, 2012). "Abnormal FBLN1 expression has been found in various diseases, including cancer, cardiovascular diseases, and diabetes." (PMID 39201719, 2024). "Concerning the vascular role of FBLN1, in diabetes or chronic kidney disease increased plasma FBLN1 levels are thought to contribute to thrombotic and cardiovascular complications." (PMID 35932462, 2022). "Our findings are in accordance with findings from earlier experimental and clinical studies which suggested links between fibulin-1, cardiovascular disease and diabetes." (PMID 23294625, 2013). "In a multivariable regression model, diabetes, creatinine, fibrinogen and central augmentation pressure were independent predictors of plasma fibulin-1." (PMID 23294625, 2013). "The first major finding of this study was a significant association between plasma fibulin-1 levels and PWV in patients with type 2 diabetes and gender- and age matched controls when adjusted for effect-modification from gender and diabetes." (PMID 23866070, 2013). "Fibulin-1 is a candidate in the pathogenesis of cardiovascular disease observed in chronic kidney disease and diabetes." (PMID 23294625, 2013). "Metformin similarly reduced Fibulin 1 levels inpatients with diabetes." (PMID 40026492, 2025).
diabetes (continued). "In addition, it was found that both fibulin-1 and arterial stiffness index were increased in patients with diabetes." (PMID 35872882, 2022). "The presence of diabetes was an independent predictor of elevated plasma fibulin-1 levels." (PMID 23294625, 2013). "In diabetes an accumulation of fibulin-1 in the arterial wall and in plasma has been described." (PMID 23294625, 2013). "Furthermore, we observed significantly increased fibulin-1 concentrations in patients with chronic kidney disease plus diabetes mellitus (median, 78 μg/mL; 74 to 113 μg/mL) compared to patients with chronic kidney disease without diabetes mellitus (median, 69 μg/mL; 49 to 79 μg/mL; p < 0.050)." (PMID 23294625, 2013). "Analysis of the proteomic abundance of proteins indicated that diabetes induced the expression levels of collagen type VI α6 (4.32 fold, p = 0.03), collagen type XVIII α1 (2.75 fold, p = 0.035), and fibulin 1 (4.12 fold, p = 0.013) compared to control tissues." (PMID 29121074, 2017). "Along these lines, analysis of the proteome profile of proteins indicated that diabetes induced the expression levels of matrix proteins such as collagen type VI α6 and type XVIII α1, fibulin 1 and transforming growth factor beta (TGF- β) in the aorta." (PMID 29121074, 2017). "The presence of diabetes, creatinine, CAP, and plasma fibrinogen concentration together explained 59% of the variability of plasma fibulin-1 concentration in patients with CKD." (PMID 23294625, 2013). "Therefore, we suggested that FBLN1 can be considered as a secondary response on the disturbed hemostasis due to its binding with fibrinogen activity, and can generalize groups with a high risk of DF (G02P, G04P, G07P and G09P) regardless of the etiology of diabetes mellitus." (PMID 33184417, 2020). "In a longitudinal cohort study, higher concentrations of fibulin-1-protein were detected in artery extracts from patients with diabetes than individuals without diabetes, and the concentrations of plasma fibulin-1 were correlated with glucose control." (PMID 28529466, 2017). "Diabetes patients treated with metformin had significantly lower fibulin-1 levels than patients not treated with metformin, 88 ± 23 vs 103 ± 34 μg/mL, p < 0.05, despite comparable glomerular filtration rates, 78 ± 16 vs 75 ± 14 mL/min/1.73 m2, p = 0.28." (PMID 23866070, 2013). "The fibulin-1 protein was found in higher concentration in the arterial wall and in plasma from patients with type 2 diabetes with long diabetes duration and CVD, compared with non-diabetics with CVD." (PMID 23866070, 2013). "However, the plasma fibulin-1 level is not a simple marker of the degree of arterial stiffening, as evidenced by lower plasma fibulin-1 concentrations in the diabetes patients." (PMID 23866070, 2013). "Patients with diabetes that were not treated with metformin had plasma fibulin-1 levels comparable to the controls, 103 ± 34 vs. 100 ± 30 μg/mL, p = 0.75, whereas metformin-treated patients had markedly lower fibulin-1 levels than controls, 88 ± 23 vs. 109 ± 29 μg/mL, p < 0.001." (PMID 23866070, 2013). "However, as testing for interaction between diabetes and fibulin-1 was only borderline significant, no firm conclusions regarding differences in the strength of the association between PWV and fibulin-1 in the diabetes group versus the control group can be made in the present study." (PMID 23866070, 2013).
prostate carcinoma (13 papers, 2007 to 2025). A carcinoma that arises from epithelial cells of the prostate gland. "Additionally, CXCL1 reduces fibulin-1 expression in prostate cancer cells and causes the activation of NF-κB, which forms a complex with histone deacetylase 1 (HDAC1)." (PMID 37108425, 2023). "As fibulin-1 regulates ECM function, changes resulting from decreased fibulin-1 expression in the ECM facilitate prostate cancer migration." (PMID 37108425, 2023). "TGF-β treatment suppresses fibulin-1 mRNA expression and protein abundance, and fibulin-1 downregulation by TGF-β reduces the ability of human bone marrow stromal cells to induce prostate cancer cell death." (PMID 30227601, 2018). "Fibulin-1 is reported to involve in the progression of many kinds of cancers, such as breast, ovarian and prostate cancer." (PMID 25234557, 2014). "FBLN1 was down-regulated in prostate cancer and in hepatocellular cancer, in which it was proposed as a novel candidate tumor suppressor." (PMID 24516561, 2014). "Real-time RT-PCR revealed GADD45A, MX1, EPB41L3/DAL1, and FBLN1 as generally downregulated in prostate cancer, whereas HOXB13 and EPB41L4B were upregulated." (PMID 17280610, 2007). "In contrast and therefore surprisingly, in prostate cancer FBLN1 appears to become generally downregulated." (PMID 17280610, 2007). "Consistently, FBLN1 downregulation has been observed in human prostate cancer, which may lead to reduced cell death and thereby promote tumorigenesis." (PMID 37870957, 2023). "FBLN1 has been reported to act as a tumor suppressor gene and to be regulated by promoter hypermethylation in gastric and prostate cancer, and in renal cell carcinoma and bladder cancer the FBLN1 promoter hypermethylation has been shown to correlate with gene expression and tumor stage." (PMID 28333958, 2017). "The decreases in laminin and Fibulin-1 expression may be related to the dissolution of the basement membrane in prostate cancer tissues." (PMID 17280610, 2007). "Biological interactions between fibulin-1 and TGF-β in tissue remodeling have been studied in respiratory diseases including pulmonary fibrosis and chronic obstructive pulmonary disease (COPD) and bone metastasis of prostate cancer." (PMID 30227601, 2018).
hepatocellular carcinoma (12 papers, 2014 to 2025). A malignant tumor that arises from hepatocytes. "On the contrary, the expression of FBLN1 is associated with hepatocellular carcinoma (HCC) progression and it is upregulated in the majority of the examined HCC tissues." (PMID 35932462, 2022). "Previous studies indicated that elevated expression of FBLN1 is associated with cancer progression, including hepatocellular carcinoma, cholangiocarcinoma, and renal cell carcinoma." (PMID 34977033, 2021). "Additionally, high methylation of the FBLN1 promoter is associated with the progression of hepatocellular carcinoma, squamous cell carcinoma, and skin cancer." (PMID 39201719, 2024). "Downregulation of FBLN1 expression has been shown to be associated with tumour progression and act as a prognostic factor in many cancers such as gastric, renal cell carcinoma, hepatocellular carcinoma and lung adenocarcinoma." (PMID 33167358, 2020). "Fibulin-1, a component of the extracellular matrix (ECM), its prognostic, pathophysiologic and diagnostic role in hepatocellular carcinoma (HCC) is still unexplored." (PMID 32612994, 2020). "Among the specifically downregulated serum proteins in LSSD-CHB patients fibulin-1 (FBLN1) is a tumor suppressor in hepatocellular carcinoma." (PMID 28025641, 2016). "Fibulin-1 has been found epigenetically silenced in gastric cancer and hepatocellular carcinoma through promoter hypermethylation." (PMID 25234557, 2014). "Fibulin-1 has been shown to promote tumor survival via activation of anti-apoptotic Notch signaling and is associated with increased immune cell infiltration in hepatocellular carcinoma (HCC), highlighting its possible involvement in tissue remodeling and immune regulation." (PMID 40948797, 2025). "Besides, fibulin-1 has been identified epigenetically silenced in gastric cancer and hepatocellular carcinoma through promoter hypermethylation." (PMID 25234557, 2014). "miR892a modulates the FBLN1, MYH7B and MST1R genes and is known to promote proliferation and invasion of hepatocellular carcinoma cells via targeting CD226." (PMID 34357026, 2021).
gastric cancer (9 papers, 2008 to 2025). A primary or metastatic malignant neoplasm involving the stomach. "Fibulin-1 is downregulated by promoter hypermethylation and promotes apoptosis in gastric cancer and hepatitis C virus (HCV)-associated HCC." (PMID 32612994, 2020). "FBLN1 (fibulin-1) was determined to be a prognostic factor in patients with gastric cancer by inhibiting cell growth and promoting apoptosis." (PMID 37056938, 2023). "In an effort to search for such genes aberrantly methylated in gastric cancer development, fibulin 1 (FBLN1) was found as a candidate TSG epigenetically downregulated in gastric cancer." (PMID 18985039, 2008). "Hypermethylation of the FBLN1 promoter was frequently (71%, 5 out of 7) detected in gastric cancer cell lines and primary gastric carcinoma tissues." (PMID 18985039, 2008). "The expression of FBLN1 in gastric cancer cell lines, before and after Aza treatment, was determined by quantitative real-time RT–PCR." (PMID 18985039, 2008). "In summary, FBLN1 was identified as a novel candidate TSG epigenetically downregulated in gastric cancer." (PMID 18985039, 2008). "Ectopic expression of FBLN1 led to the growth inhibition of gastric cancer cells through the induction of apoptosis." (PMID 18985039, 2008). "Although promoter methylation frequently inactivates FBLN1 in gastric cancer cell lines, we cannot exclude the presence of other mechanisms for the loss of function of FBLN1, such as defects in histone remodelling." (PMID 18985039, 2008). "The ectopic expression of FBLN1 led to the growth inhibition of gastric cancer cells, indicating that FBLN1 functions as a novel TSG epigenetically silenced in gastric cancer." (PMID 18985039, 2008). "Fibulin 1 was identified in this study as a novel candidate TSG epigenetically inactivated in gastric cancer." (PMID 18985039, 2008). "FBLN1 expression was downregulated in all of gastric cancer cell lines used (100%, 7 out of 7) and the primary gastric carcinoma tissues (84%, 86 out of 102) and significantly restored after pharmacological demethylation." (PMID 18985039, 2008). "Fibulin 1 expression was significantly upregulated in all five gastric cancer cell lines (AGS, Kato III, MKN28, MKN45 and NCI-N87) after Aza treatment." (PMID 18985039, 2008). "Similar results were reported for serum exosomal fibulin-1 in patients with gastric cancer." (PMID 36034715, 2022). "In summary, we identified FBLN1 as a novel candidate TSG epigenetically silenced in gastric cancer." (PMID 18985039, 2008). "Other methylation analyses with higher resolution, such as quantitative methylation-specific analysis using sequenom or Taqman real-time PCR, are warranted to assess whether FBLN1 promoter methylation is useful for detecting early gastric cancer and predicting prognosis." (PMID 18985039, 2008). "miR647 modulates FBLN1, FN1, and MST1R genes and has a tumor-promoting role in gastric cancer via repression of TP73." (PMID 34357026, 2021). "In this study, we focused on fibulin 1 (FBLN1), which was significantly upregulated after pharmacological demethylation in all (5 out of 5) gastric cancer cell lines used." (PMID 18985039, 2008). "However, whether FBLN1 functions as a TSG in gastric cancer remains unknown." (PMID 18985039, 2008). "Full methylation was detected in five gastric cancer cell lines, whereas the other two cell lines showed partial or no methylation of FBLN1 CGI." (PMID 18985039, 2008). "In addition, the expression of FBLN1 was downregulated in all five gastric cancer cell lines and two extra gastric cancer cell lines (SNU1 and SNU16), indicating that FBLN1 is most likely one novel TSG that is silenced through promoter hypermethylation in gastric cancer." (PMID 18985039, 2008).
ovarian carcinoma (9 papers, 2003 to 2024). A malignant neoplasm originating from the surface ovarian epithelium. "The recent observation that ovarian carcinomas exhibit an increased ratio of fibulin-1C : 1D mRNA suggests that these fibulin-1 variants exhibit differing functions." (PMID 12644824, 2003). "In our samples, Fbln1, −3, −4 and -5 were significantly downregulated in epithelial ovarian cancer (EOC) relative to benign ovarian tissue." (PMID 29581841, 2018). "It is noteworthy that, previous studies have reported that FBLN1 expression is elevated in breast tumors and ovarian cancer cells." (PMID 25866482, 2015). "Fibulin-1 is a secreted Ca2+-binding plasma and extracellular matrix protein that is induced by estrogens in ovarian cancer cells." (PMID 26161649, 2015). "FBLN1, a calcium-binding, acidic glycoprotein of extracellular matrix, is positively correlated with ovarian cancer progression; and elevated expression of KLK3 and TMPRSS2 have been associated with PCa aggressiveness." (PMID 21134280, 2010). "In the case of ovarian cancer, while fibulin-1 mRNA is produced by tumour-derived epithelial cells, fibulin-1 protein has been shown to accumulate in stroma surrounding the tumour cells." (PMID 12644824, 2003). "Full-length fibulin-1 protein is known to be secreted by oestrogen-responsive ovarian cancer cells upon exposure to oestradiol." (PMID 12644824, 2003). "In addition, fibulin-1 expression was previously shown to be inversely correlated with PR protein levels in ovarian carcinomas." (PMID 12644824, 2003). "Indeed, there are only two reports to date (both from the same research group) that document the expression of fibulin-1 in human cancer, specifically ovarian carcinoma." (PMID 12644824, 2003). "The elevated expression of fibulin-1 protein seen in breast and ovarian carcinomas may be reflective of a similar role in vivo." (PMID 12644824, 2003). "Upregulation of fibulin-1 protein may be useful as a marker for breast and ovarian cancer." (PMID 12644824, 2003). "In this study, we also showed that parent genes such as BCLAF1, FBLN1, ARHGAP23, STON2, UBQLN4, and ATP2B1 were significantly positively correlated with the survival rate of patients with ovarian cancer." (PMID 35978436, 2022). "We found that the expression of six genes (BCLAF1, FBLN1, ARHGAP23, STON2, UBQLN4, and ATP2B1) had a significant positive correlation with the survival rate of patients with ovarian cancer." (PMID 35978436, 2022).